SMIM39 (small integral membrane protein 39)
Gene: Protein-coding gene on chromosome 2 (131,034,928 to 131,047,253, forward strand). Ensembl gene ENSG00000284479.
Subcellular location: Membrane
Gene Ontology:
Cellular component: membrane
Genetic constraint (gnomAD): Loss-of-function variants: 1 observed, 0.54 expected, observed/expected ratio (o/e) 1.85, 90% interval 0.34 to 1.92. That is too few expected variants to judge how well the gene tolerates losing a copy. Missense variants: 68 observed, 67.43 expected, observed/expected ratio (o/e) 1.01, 90% interval 0.83 to 1.23. Synonymous variants: 31 observed, 34.69 expected, observed/expected ratio (o/e) 0.89, 90% interval 0.67 to 1.21.
Homologues: Orthologues: mouse Smim39 (93% identical).